SNORA79 (small nucleolar RNA, H/ACA box 79)
Synonyms: ACA65; SNORA79A
Gene: Small nucleolar RNA gene on chromosome 14 (81,202,695 to 81,202,834, reverse strand). Ensembl gene ENSG00000221303.
Gene Ontology:
Biological process: RNA processing
Cellular component: nucleolus
Homologues: Orthologues: chimpanzee SNORA79 (99% identical), macaque SNORA79 (99% identical), dog SNORA79 (94% identical), pig SNORA79 (91% identical), rabbit SNORA79 (91% identical), rat LOC120095776 (88% identical), mouse Gm24241 (72% identical). Paralogues in human: SNORA79B (69% identical).